IFNA10 (interferon alpha 10)
Description:
Produced by macrophages, IFN-alpha have antiviral activities. Interferon stimulates the production of two enzymes: a protein kinase and an oligoadenylate synthetase.
Synonyms: IFN-alphaC
Tractability: Antibody: a drug acting on it is in phase 2 or 3 trials; its Gene Ontology location is reachable by antibodies, with high confidence; UniProt places it where antibodies can reach, with medium confidence; UniProt predicts a signal peptide or a membrane-spanning region.
Gene: Protein-coding gene on chromosome 9 (21,206,181 to 21,207,143, reverse strand). Ensembl gene ENSG00000186803.
Subcellular location: Secreted
Pathways (Reactome):
Immune System: Interferon alpha/beta signaling; Regulation of IFNA/IFNB signaling; TRAF6 mediated IRF7 activation
Disease: Evasion by RSV of host interferon responses; SARS-CoV-2 activates/modulates innate and adaptive immune responses
Hemostasis: Factors involved in megakaryocyte development and platelet production
Gene Ontology:
Molecular function: cytokine activity; type I interferon receptor binding; cytokine receptor binding
Biological process: adaptive immune response; B cell activation involved in immune response; cellular response to virus; humoral immune response; natural killer cell activation involved in immune response; response to exogenous dsRNA; T cell activation involved in immune response; type I interferon-mediated signaling pathway; defense response
Cellular component: extracellular region
Genetic constraint (gnomAD): Loss-of-function variants: 1 observed, 0.29 expected, observed/expected ratio (o/e) 3.45. That is too few expected variants to judge how well the gene tolerates losing a copy. Missense variants: 246 observed, 209.79 expected, observed/expected ratio (o/e) 1.17, 90% interval 1.06 to 1.3. Synonymous variants: 96 observed, 79.28 expected, observed/expected ratio (o/e) 1.21, 90% interval 1.03 to 1.43.
Homologues: Orthologues: macaque IFNA10 (92% identical), macaque IFNA21 (91% identical), pig IFN-ALPHA-9 (69% identical), pig IFN-ALPHA-13 (68% identical), pig IFN-ALPHA-15 (68% identical), pig IFN-ALPHA-8 (68% identical), pig IFNA1 (67% identical), pig IFN-ALPHA-4 (66% identical), pig IFN-ALPHA-17 (64% identical), pig IFN-ALPHA-1 (63% identical), pig IFN-ALPHA-10 (63% identical), rabbit IF1AD2 (63% identical), and 32 more. Paralogues in human: IFNA4 (96% identical), IFNA17 (95% identical), IFNA7 (92% identical), IFNA21 (91% identical), IFNA16 (87% identical), IFNA14 (84% identical), IFNA5 (83% identical), IFNA6 (81% identical), IFNA2 (80% identical), IFNA8 (80% identical), IFNA13 (79% identical), IFNA1 (79% identical), and 4 more.
Diseases named in the same sentence as IFNA10 in open-access papers:
IFNA10 is named in the same sentence as 9 diseases in open-access papers, as found by Europe PMC text mining. Sharing a sentence is not in itself a finding about the gene and the disease. The quoted sentences say what the papers report.
COVID-19 (4 papers, 2021 to 2025). A disease caused by infection with severe acute respiratory syndrome coronavirus 2. "In addition, the rs28368148 (CG genotype) correlating with the interferon-alpha-10 (IFNA10) gene was found strongly correlating with severe COVID-19, whereas the rs8178521 (CT genotype) of the IL-10-receptor-beta (IL-10RB) gene was found weakly correlated with severe COVID-19." (PMID 36941580, 2023). "This exercise revealed that, whereas the DS IFN score tracks preferentially with IFNG and IFNL1 in DS, this same ISG signature correlates significantly with eight different IFNs in COVID-19, five of which are type I IFNs (i.e., IFNA2, IFNA7/17/21, IFNA1, IFNA4/16, and IFNA10)." (PMID 37379383, 2023).
colitis (1 paper, 2015). Inflammation of the colon. "To further evaluate the function of IFNA4 and IFNA10 during inflammation, we administrated recombinant IFNA4 and IFNA10 in a DSS-induced acute colitis model." (PMID 26000985, 2015).
type 1 diabetes (1 paper, 2021). "IFNA1 expression was increased by 75% (p = 1.30 × 10−3, 95% CI −0.44, −0.09) and IFNA10 expression was increased by 136% (p < 1.00 × 10−4, 95% CI −0.50, −0.18) in individuals with new-onset type 1 diabetes." (PMID 33973017, 2021).
IFNA10 also shares sentences with these, for which no sentence is quoted: infection (3 papers); bacterial infections (1); Crohn disease (1); fungal infections (1); lupus nephritis (1); viral infections (1).